DDX24 (DEAD-box helicase 24)
Diseases named in the same sentence as DDX24 in open-access papers (continued):
Sharing a sentence is not in itself a finding about the gene and the disease.
tumor (10 papers, 2017 to 2026). "Immunohistochemical (IHC) staining analysis of xenograft tumor tissues confirmed a marked reduction of DDX24 in tumors derived from DDX24-deficient cells." (PMID 39897555, 2025). "DEAD-box helicase 24 (DDX24) is a tumor-associated gene that is often used as a marker to assess tumor risk and treatment efficacy." (PMID 39229278, 2024). "The tumor suppression induced by K11E or E271K mutation of DDX24 is expected to provide a novel idea or direction for tumors prevention and treatment, especially for those tumors in which DDX24 plays an oncogenic role in proliferation." (PMID 35370459, 2022). "In summary, our present work verified K11E or E271K mutation led to “loss-of-function” of DDX24 in cell proliferation and tumor bearing mice by using a CHO cell model." (PMID 35370459, 2022). "Our existing study provided evidence that DDX24 formed heteroligomer with the mutated DDX24 proteins, therefore “dominant negatives” may be the underline mechanism that these mutations in cell and in tumor bearing mouse changed the oncogenicity of DDX24." (PMID 35370459, 2022). "Intriguingly, the higher level of DDX24 protein was linked to the poor tumor grade of LUAD." (PMID 35864588, 2022). "The results demonstrated that the reduction in tumor growth induced by DDX24 knockdown was significantly attenuated when IKBKG-L was concurrently silenced in vivo." (PMID 39897555, 2025). "Functional rescue experiments confirm that the long IKBKG isoform-mediated autophagy confers the anti-tumor effects of DDX24 depletion." (PMID 39897555, 2025). "Bioinformatics analysis revealed a critical role for DDX24 in splicing regulation, affecting the splicing of numerous autophagy- and tumor-related genes." (PMID 39897555, 2025). "First, we resorted to the clinical proteomic tumor analysis consortium (CPTAC) database to explore DDX24 expression in NSCLC." (PMID 35864588, 2022). "DDX24 was highly expressed in tumor tissue formed by CHO-WT-DDX24, CHO-K11E-DDX24 or CHO-E271K-DDX24, except CHO-Vector." (PMID 35370459, 2022). "DDX24 was reported to be related to tumors closely, thus this study aims to explore how K11E and E271K affect DDX24-function in tumor proliferation." (PMID 35370459, 2022). "In the malignant metastatic model, the numbers of metastasis tumor nodules observed on the surface of lungs were much less than when DDX24 was silenced." (PMID 35864588, 2022). "In this study, bioinformatic analysis revealed that DDX24 was associated with poor survival in HCC cases, and significantly related to the pathways modulating tumor development." (PMID 36310384, 2022). "The level of DDX24 protein is elevated in all but one of the tumor cell lines we tested relative to BJ-hTERT fibroblasts." (PMID 28223711, 2017). "Importantly, depleted DDX24 resulted in significantly reduced tumor growth rates and smaller tumor volumes compared to control groups." (PMID 39897555, 2025). "To investigate whether DDX24 regulated the anti-tumor effect of SFN against HCC growth in vivo, we used a subcutaneous mouse HCC xenograft model." (PMID 36310384, 2022). "However, to our knowledge, this is the first identification of DDX24 as a target for selective inhibition of tumor growth." (PMID 28223711, 2017). "Antisense oligonucleotide-mediated inhibition of SNRPF disrupts this feedback loop, downregulates DDX24 and E2F4 via IR, and significantly impairs tumor growth in vitro, in vivo, and in patient-derived xenografts." (PMID 42107058, 2026). "To further elucidate the impact of DDX24 on IKBKG splicing, we examined the splicing of IKBKG in tumor tissues from xenograft models." (PMID 39897555, 2025). "Functionally, LINC02551 acts as a tumor-promoting factor though suppressing the interaction between DDX24 and a E3 ligase TRIM27, thus promoting degradation of DDX24." (PMID 38545555, 2024).
tumor (continued). "Recent studies have reported that RNA helicases play a role in the progression of a variety of tumor types, including DHX9, DHX15, DDX24, DHX29, and DHX36." (PMID 37958405, 2023). "DDX24 expression was upregulated in NSCLC cell lines and tumors of patients, particularly those with high tumor grades." (PMID 35864588, 2022). "In conclusion, by means of a bioinformatics analysis, the highlighted findings of our research identified DDX24 as an adverse indicator of HCC prognosis and that it was significantly related to the pathways modulating tumor development." (PMID 36310384, 2022). "This study disclosed that DDX24 was highly expressed in NSCLC patients, especially those with high tumor grades." (PMID 35864588, 2022). "To further explore the tumor-suppressive effects of DDX24 depletion in vivo, driven by the increased production of the long isoform of IKBKG, we conducted xenograft mouse experiments using cell lines with simultaneous silencing of DDX24 and IKBKG-L." (PMID 39897555, 2025). "Although we did not knockdown or knockout the endogenous expression of DDX24 in above human tumor cells, MHCC-97L, KYSE410 and HeLa cells transfected with mutant DDX24 still exhibited proliferation suppression, which implied these mutations have lost these roles in cellular proliferation." (PMID 35370459, 2022). "Proliferation assays in human tumor cells showed that the expression of K11E or E271K DDX24 may inhibit relate cell proliferation in tumors with high expression of DDX24 or bad prognosis of DDX24, but not in tumors with low expression of DDX24 or none-risk prognostic of DDX24." (PMID 35370459, 2022).
infection (3 papers, 2013 to 2024). The state of being infected such as from the introduction of a foreign agent such as serum, vaccine, antigenic substance or organism. "We noted that suppression of DDX24 robustly prevented the replication of this virus as determined by luciferase levels and viral titers 8 or 24 hours post infection." (PMID 24204270, 2013). "However, during infection with Kaposi’s sarcoma-associated herpesvirus (KSHV), DDX24 and DDX49 bind to multiple KSHV mRNAs and reduce viral reactivation." (PMID 39212449, 2024). "The DDX24 and DDX49 helicases were observed to bind to several identical KSHV RNAs during lytic infection with varying degrees." (PMID 36298642, 2022). "DDX24 and DDX49 also interact with viral RNA to control infections." (PMID 39212449, 2024). "Understanding the molecular mechanisms by which DDX24 and DDX49 inhibit reactivation could lead to therapeutic strategies for EBV and KSHV malignancies whose pathogenesis is driven by both the latent and lytic phases of infection." (PMID 36298642, 2022).
DDX24 also shares sentences with these, for which no sentence is quoted: Alzheimer disease (1 paper); cervical squamous cell carcinoma (1); diabetes (1); endocervical adenocarcinoma (1); esophageal carcinoma (1); Kaposi's sarcoma (1); memory impairment (1); non-small cell lung carcinoma (1); Obesity (1); prostate adenocarcinoma (1).